PTPN3 (protein tyrosine phosphatase non-receptor type 3)
Description:
May act at junctions between the membrane and the cytoskeleton. Possesses tyrosine phosphatase activity.
Synonyms: PTP-H1; PTPH1
Tractability: Small molecule: a structure with a bound ligand is known. Antibody: its Gene Ontology location is reachable by antibodies, with high confidence; UniProt places it where antibodies can reach, with medium confidence. PROTAC: ubiquitination databases record sites on it; a small molecule that binds it is known.
Target class: Tyrosine protein phosphatase; Enzyme; Phosphatase; Protein Phosphatase
Gene: Protein-coding gene on chromosome 9 (109,375,466 to 109,498,333, reverse strand). Ensembl gene ENSG00000070159.
Subcellular location: Cell membrane; Cytoplasm, cytoskeleton
Pathways (Reactome):
Signal Transduction: EGFR downregulation; Negative regulation of MAPK pathway
Gene Ontology:
Molecular function: ATPase binding; phosphotyrosine residue binding; protein binding; protein tyrosine phosphatase activity; sodium channel regulator activity; cytoskeletal protein binding
Biological process: negative regulation of membrane protein ectodomain proteolysis; negative regulation of mitotic cell cycle; regulation of membrane depolarization during action potential; regulation of sodium ion transmembrane transport; MAPK cascade; negative regulation of epidermal growth factor receptor signaling pathway
Cellular component: cytoplasm; cytoplasmic side of plasma membrane; cytosol; plasma membrane; cytoskeleton
Genetic constraint (gnomAD): Loss-of-function variants: 94 observed, 127.88 expected, observed/expected ratio (o/e) 0.74, 90% interval 0.62 to 0.87. The upper end of that interval is the gene's LOEUF score, 0.87, which puts it in group 3 of 6, group 1 being the genes least tolerant of losing a copy. Missense variants: 1,099 observed, 1,163.8 expected, observed/expected ratio (o/e) 0.94, 90% interval 0.9 to 0.99. Synonymous variants: 391 observed, 433.62 expected, observed/expected ratio (o/e) 0.9, 90% interval 0.83 to 0.98.
Homologues: Orthologues: chimpanzee PTPN3 (99% identical), macaque PTPN3 (96% identical), guinea pig PTPN3 (93% identical), mouse Ptpn3 (92% identical), dog PTPN3 (92% identical), rat Ptpn3 (92% identical), pig PTPN3 (89% identical), rabbit PTPN3 (85% identical), tropical clawed frog ptpn3 (73% identical), zebrafish ptpn3 (53% identical). Paralogues in human: PTPN4 (52% identical), PTPRB (21% identical), PTPRD (21% identical), PTPRF (20% identical), PTPRS (20% identical), PTPN21 (19% identical), PTPN23 (19% identical), PTPRT (18% identical), PTPRM (18% identical), PTPRZ1 (18% identical), PTPN13 (18% identical), PTPN14 (18% identical), and 23 more.
Diseases named in the same sentence as PTPN3 in open-access papers:
PTPN3 is named in the same sentence as 47 diseases in open-access papers, as found by Europe PMC text mining. Sharing a sentence is not in itself a finding about the gene and the disease. The quoted sentences say what the papers report.
breast carcinoma (8 papers, 2015 to 2024). "A previous study has indicated that PTPN3 was overexpressed in breast cancer, and stimulates breast cancer growth through regulating vitamin D receptor (VDR) expression." (PMID 38173048, 2024). "Evidence has indicated that PTPN3 can enhance metastasis and invasion in several cancer types, such as breast cancer, ovarian cancer, and gastric cancer." (PMID 38173048, 2024). "A strongly positive expression of PTPN3 was observed in KIRC, and LUAD, followed by a moderately positive expression of PTPN3 in breast cancer." (PMID 38173048, 2024). "IHC was used to investigate and confirm the various expression levels of PTPN3 in various malignancies, including breast cancer, lung cancer, sarcoma, and kidney renal clear cell carcinoma in our clinical cohorts." (PMID 38173048, 2024). "We further validated PTPN3 expression by IHC in 4 different cancers by our cohorts, including breast cancer, lung adenocarcinoma, kidney renal clear cell carcinoma, and sarcoma." (PMID 38173048, 2024). "PTPN3 was also reported in breast cancer by dephosphorylating the epidermal growth factor receptor (EGFR), increasing sensitivity to tyrosine kinase inhibitors, and by regulation of the vitamin D receptor expression and stability, which stimulates breast cancer growth." (PMID 37200868, 2023). "Furthermore, PTPN3 has been reported to dephosphorylate EGFR, thus increasing sensitivity to tamoxifen and tyrosine kinase inhibitors (TKIs) in breast cancer." (PMID 38173048, 2024). "MKLN1 has been previously associated with childhood asthma, SORBS1 with suicide risk and childhood obesity in Hispanics, SLC1A2 with fatty acid levels, essential tremor, and other traits, EPB41L4B with wound healing, PTPN3 with cancer, and FGF3 with breast cancer and deafness." (PMID 26569114, 2015).
lung carcinoma (7 papers, 2016 to 2024). "In lung cancer, PTPN3 has been shown to limit cellular proliferation and invasion by increasing EGFR endocytic degradation." (PMID 38173048, 2024). "PTPN3 suppresses lung cancer cell proliferation and migration by counteracting Src-mediated disheveled-associated activator of morphogenesis 1 (DAAM1) activation and actin polymerization and by promoting EGFR endocytic degradation." (PMID 35957898, 2022). "However, a recent study showed that PTPN3 inhibits lung cancer cell proliferation and migration by promoting the endocytic degradation of EGFR, indicating that PTPN3 may act as a tumour suppressor in lung cancer through its modulation of EGFR signalling." (PMID 27833130, 2016). "Other less common rearrangements detected in lung cancer patients include KIF5B-ALK (kinesin family member 5B-ALK), TFG (trafficking from ER to golgi regulator)-ALK, KLC1 (kinesin light chain-1)-ALK, PTPN3 (protein tyrosine phosphatase non-receptor type 3)-ALK, STRN (striatin)-ALK." (PMID 39457620, 2024). "Furthermore, PTPN3, PTPN6, PTPN12 and PTPN13 play tumor suppressor roles in lung cancer." (PMID 35957898, 2022).
colorectal cancer (6 papers, 2016 to 2024). A primary or metastatic malignant neoplasm that affects the colon or rectum. "PTPN3 (also known as PTPH1) was also reported to be strongly correlated with diverse cancers including colorectal cancer and gastric adenocarcinoma." (PMID 32382535, 2020). "Upregulated miR-497-5p inhibits colorectal cancer cell growth by targeting PTPN3." (PMID 34772428, 2021). "Previous studies on the mutational analysis of the tyrosine phosphatase gene superfamily in human cancers identified 83 somatic mutations in six PTPs (PTPRF, PTPRG, PTPRT, PTPN3, PTPN13, PTPN14), affecting 26% of colorectal cancers and a smaller fraction of lung, breast and gastric cancers." (PMID 27833130, 2016).
ovarian carcinoma (6 papers, 2016 to 2024). A malignant neoplasm originating from the surface ovarian epithelium. "The high expression of PTPN3 was significantly associated with poor overall survival of ovarian cancer patients." (PMID 27833130, 2016). "However, the mutation rate of PTPN3 is relatively low in ovarian cancer, according to the TCGA dataset." (PMID 27833130, 2016). "Moreover, high expression of PTPN3 was significantly associated with poor overall survival in ovarian cancer patients." (PMID 27833130, 2016). "In ovarian cancer cells resistant to cisplatin and doxorubicin, PTPN3 is significantly elevated and can support chemotherapy resistance as well as cancer stemness." (PMID 38173048, 2024). "PTPN3 expression was dramatically elevated in both cisplatin- and doxorubicin-resistant ovarian cancer cells compared to parental cells, and inhibiting PTPN3 restored sensitivity to both drugs." (PMID 38173048, 2024). "Strikingly, PTPN3 confers chemoresistance and tumor stem cell-like characteristics to ovarian cancer cells." (PMID 35957898, 2022). "Other groups have reported that a protein Tyrosine phosphatase PTPN3 gene expression increases in cisplatin and doxorubicin‐resistant ovarian cancer cells." (PMID 32031337, 2020). "PTPN3/PTPH1 supported tumor growth and metastasis in human glioma and promoted resistance and stem cell like characteristics in ovarian cancers." (PMID 30875834, 2019). "The results showed that silencing PTPN3 significantly contributed to increasing the sensitivity of resistant ovarian cancer cells to cisplatin and doxorubicin." (PMID 27833130, 2016). "The effect of stable silencing of PTPN3 on the tumorigenicity of resistant ovarian cancer cells was further investigated in a mouse model in vivo." (PMID 27833130, 2016). "The cell growth curves indicated that cell growth was dramatically reduced by silencing PTPN3 in both cisplatin and doxorubicin resistant ovarian cancer cells." (PMID 27833130, 2016). "Silencing of PTPN3 also inhibited cell cycle progression, migration and stemness, and reduced the tumorigenicity of resistant ovarian cancer cells." (PMID 27833130, 2016). "To investigate the critical role of PTPN3 in ovarian cancer drug resistance and cell cycle progression, we examined the effects of silencing of PTPN3 on resistant ovarian cancer cell growth, migration and drug resistance." (PMID 27833130, 2016). "Subsequent cell cycle analysis by flow cytometry indicated that silencing of PTPN3 significantly increased the G0-G1 phase cell population and decreased the S phase cell population in both cisplatin and doxorubicin resistant ovarian cancer cells." (PMID 27833130, 2016). "The tumour sphere formation assay showed that stable silencing PTPN3 significantly inhibited the sphere forming ability of both cisplatin and doxorubicin resistant ovarian cancer cells." (PMID 27833130, 2016). "Silencing PTPN3 inhibits resistant ovarian cancer cell growth, cell cycle progression, migration, drug resistance, stemness and tumorigenicity." (PMID 27833130, 2016). "Meanwhile, the expression of PTPN3 was found to be regulated by miR-199 in resistant ovarian cancer cells." (PMID 27833130, 2016). "Immunodeficient Balb/C mice were subcutaneously injected with resistant ovarian cancer cells that had been previously stably transfected with PTPN3 shRNA or shScramble control." (PMID 27833130, 2016). "Here, we found that protein tyrosine phosphatase PTPN3 gene expression was substantially increased in both cisplatin and doxorubicin-resistant ovarian cancer cells." (PMID 27833130, 2016). "Silencing of PTPN3 restored sensitivity to cisplatin and doxorubicin in resistant ovarian cancer cells." (PMID 27833130, 2016). "Silencing PTPN3 significantly suppressed the migration rates of both cisplatin and doxorubicin resistant ovarian cancer cells." (PMID 27833130, 2016).
ovarian carcinoma (continued). "Next, we further detected the protein expression of PTPN3 in resistant ovarian cancer cells after transfection with miR-199 mimics or control." (PMID 27833130, 2016). "Down-regulation of PTPN3 also inhibited cell cycle progression, migration, stemness in vitro and the tumorigenicity of resistant ovarian cancer cells in vivo." (PMID 27833130, 2016). "The results reported here provide evidence that PTPN3 regulates sensitivity to cisplatin and doxorubicin in ovarian cancer cells." (PMID 27833130, 2016). "The results show that overexpression of miR-199 decreased the expression of PTPN3 in resistant ovarian cancer cells." (PMID 27833130, 2016). "Abnormal expression of the miR-199 cluster, for example, has been confirmed to increase the sensitivity of ovarian cancer cells to DDP through silencing the expression of protein tyrosine phosphatase non-receptor type 3 (PTPN3), integrin subunit beta 8 (ITGB8) and discoidin domain receptor 1 (DDR1)." (PMID 34512721, 2021). "Moreover, PTPN3 silencing restored the sensitivity of resistant ovarian cancer cells to cisplatin and doxorubicin." (PMID 27833130, 2016). "We next examined whether PTPN3 is a critical molecule for resistant ovarian cancer cell migration using the Transwell migration assay." (PMID 27833130, 2016). "Here, the expression of PTPN3 was observed to be substantially increased in both cisplatin and doxorubicin resistant ovarian cancer cells through the genomic analysis of cisplatin and doxorubicin resistant cells compared with the parental ovarian cancer cells." (PMID 27833130, 2016). "After demonstrating the important roles of PTPN3 in resistant ovarian cancer cells, we next investigated whether miRNAs regulate the expression of PTPN3." (PMID 27833130, 2016). "We found that the expression of PTPN3 was regulated by miR-199 in resistant ovarian cancer cells." (PMID 27833130, 2016). "In the present study, highly increased expression of PTPN3 was also detected in around one third of clinical ovarian cancer tissue samples, but was not detectable in normal ovarian tissue samples." (PMID 27833130, 2016). "Importantly, the highly increased expression of PTPN3 was also detected in approximately one third of the clinical ovarian cancer tissue samples, but not detectable in normal ovarian tissue samples." (PMID 27833130, 2016).
cholangiocarcinoma (5 papers, 2016 to 2024). A carcinoma that arises from the intrahepatic biliary tree (intrahepatic cholangiocarcinoma) or from the junction, or adjacent to the junction, of the right and left hepatic ducts (hilar cholangiocarcinoma). "In cholangiocarcinoma more than 40% of PTPN3 somatic mutations, activation of PTPN3 mutations promotes cancer cell proliferation and migration and is linked to cancer recurrence." (PMID 35957898, 2022). "Activating mutations in PTPN3/PTPH1 were shown to promote cholangiocarcinoma cell proliferation and migration and were associated with tumor recurrence in colon carcinoma patients." (PMID 30875834, 2019). "Recently, activating mutations in PTPN3 have been shown to promote cholangiocarcinoma cell proliferation and migration and were associated with tumour recurrence in patients." (PMID 27833130, 2016). "Mutations in PTPN3 have been detected in 41.1% of cholangiocarcinomas." (PMID 27833130, 2016). "The high gene alteration rate of PTPN3 was detected in uterine corpus endometrial carcinoma, bladder urothelial carcinoma, skin cutaneous melanoma, stomach adenocarcinoma, cholangiocarcinoma, colorectal adenocarcinoma, and lung squamous cell carcinoma with > 2% mutation frequency." (PMID 38173048, 2024). "Examples notably include the promotion of cholangiocarcinoma cell proliferation and migration by gain-of-function mutations or increased expression of the protein tyrosine phosphatase non-receptor type 3 (PTPN3) than in nontumor tissues." (PMID 37200868, 2023).
gastric cancer (4 papers, 2021 to 2024). A primary or metastatic malignant neoplasm involving the stomach. "In gastric cancer cells, PTPN3 loss has proven to heighten angiogenesis and tumor metastasis." (PMID 34884670, 2021). "Previous studies have found a statistically significant correlation between PTPN3 and the differentiation status of gastric cancer tissue." (PMID 38173048, 2024). "It has been found that miR-574-5p can inhibit the expression of PTPN3, and promote angiogenesis in gastric cancer cells by enhancing phosphorylation of p44/42 MAPK." (PMID 38173048, 2024). "Incubating human umbilical vein endothelial cells (HUVECs) in conditioned media from PTPN3 KD gastric cancer cells resulted in elevated cell viability, migration, invasion, and more robust tube formation of HUVECs." (PMID 34884670, 2021). "For instance, miR-574-5p targets PTPN3 to enhance angiogenesis in gastric cancer." (PMID 38955795, 2024). "One study identified that knocking down PTPN3 enhanced production of VEGFA in gastric cancer cells." (PMID 34884670, 2021). "In gastric cancer cells, miR-574-5p promotes angiogenesis by increasing p44/42 MAPK phosphorylation through the inhibition of PTPN3 expression." (PMID 39125625, 2024). "PTPN3, also known as PTPH1, is a non-receptor, tyrosine-specific tumor suppressor PTP in gastric cancer." (PMID 34884670, 2021).
stomach adenocarcinoma (3 papers, 2020 to 2024). "Regarding gastric adenocarcinoma, there was a considerable upregulation of PTPN3, which was linked with the pathological grade." (PMID 38173048, 2024).
intrahepatic cholangiocarcinoma (2 papers, 2020 to 2024). A carcinoma that arises from the intrahepatic bile duct epithelium in any site of the intrahepatic biliary tree. "While another study illustrated that elevated PTPN3 expression promotes tumor recurrence and is detrimental to the prognosis of intrahepatic cholangiocarcinoma patients." (PMID 32536826, 2020).
acromegaly (1 paper, 2015). Acromegaly is an acquired disorder related to excessive production of growth hormone (GH) and characterized by progressive somatic disfigurement (mainly involving the face and extremities) and systemic manifestations. "We also identified several novel transcriptional changes, some of which may be important for GH/IGF responses (PTPN3 and PTPN4) and the effects of acromegaly on growth and proliferation." (PMID 26087292, 2015).
autoimmune disease (1 paper, 2015). A disorder resulting from loss of function or tissue destruction of an organ or multiple organs, arising from humoral or cellular immune responses of the individual to their own tissue constituents. "The observed substantial reduction of the PTPN3 mRNA levels in dogs carrying the risk haplotypes may cause a sustained activation of TCR signaling and lead to development of autoimmune disease." (PMID 26057447, 2015).
glioblastoma (1 paper, 2022). The most malignant astrocytic tumor (WHO grade IV). "Likewise, PTPN2 and PTPN3 are correlated with poor patient prognosis in glioblastoma (GBM)." (PMID 35957898, 2022).
hepatocellular carcinoma (1 paper, 2021). A malignant tumor that arises from hepatocytes. "In this study, we found that the effects of PTPN3 overexpression on HBV infection in hepatoma cells are multiple, suggesting that PTPN3 could have a significant and pleiotropic role in the HBV replication." (PMID 33441627, 2021).
Insulin resistance (1 paper, 2025). Increased resistance towards insulin, that is, diminished effectiveness of insulin in reducing blood glucose levels. "Conversely, aberrant PTPN3 expression is associated with insulin resistance and reduced caudal fat accumulation." (PMID 41153973, 2025).
kidney cancer (1 paper, 2024). Primary or metastatic malignant neoplasm involving the kidney. "Consistent with our findings, prior research has indicated that PTPN3 overexpression could inhibit kidney cancer progression by suppressing the AKT signaling pathway and served as a favorable prognostic factor in patients with KIRC, which is consistent with our results." (PMID 38173048, 2024).
large cell neuroendocrine carcinoma (1 paper, 2022). A usually aggressive carcinoma composed of large malignant cells which display neuroendocrine characteristics. "Furthermore, inhibition of PTPN3 in lymphocytes expands the proportion of tumor-infiltrating lymphocytes and activated lymphocyte cytotoxicity, as well as the anticancer effect on small cell lung cancer (SCLC) and large cell neuroendocrine carcinoma (LCNEC)." (PMID 35957898, 2022).
renal cell carcinoma (1 paper, 2024). "Our result revealed that PTPN3 expression was significantly higher in renal cell carcinoma patients who did not respond to anti-PD-1/PD-L1 treatment." (PMID 38173048, 2024).
sarcoma (1 paper, 2024). A usually aggressive malignant neoplasm of the soft tissue or bone. "Weakly positive PTPN3 expression was detected in patients with sarcoma." (PMID 38173048, 2024).
small cell lung carcinoma (1 paper, 2024). Small cell lung cancer (SCLC) is a highly aggressive malignant neoplasm, accounting for 10-15% of lung cancer cases, characterized byrapid growth, and early metastasis. "It has been found that PTPN3 inhibition significantly contributes to enhancing the activation and functions of activated lymphocytes, and has anti-cancer effects on small-cell lung cancer (SCLC) and large-cell neuroendocrine carcinoma (LCNEC)." (PMID 38173048, 2024).